CRP (C-reactive protein)
Diseases named in the same sentence as CRP in open-access papers (continued):
Sharing a sentence is not in itself a finding about the gene and the disease.
Sepsis (continued). "Thus, thromboelastometry lysis index and procalcitonin, but not interleukin 6 and C-reactive protein, are capable of detecting patients with severe sepsis in critically ill adults." (PMID 20929576, 2010). "Serum CRP values increase during the postoperative period after cardiac surgery even in the absence of infection and even if serum PCT seems to be a valuable marker of sepsis, its accuracy remains debatable and its cost may be of concern." (PMID 19912638, 2009). "The majority of patients in our study had abnormal respiratory secretions (hemorrhagic secretions or increased quantity of secretions), abnormal chest radiographs, and increased white blood cell and C-reactive protein values, but fever and changes of severe sepsis were not consistently evident." (PMID 19742269, 2008). "In patients with multiple trauma due to an accident, the PCT level provides more information than the CRP level since only moderate amounts of PCT are induced, and higher concentrations correlate with more severe trauma and a higher frequency of various complications, including sepsis and infection." (PMID 16356205, 2006). "In this study, we tested the hypothesis that CRP is associated with hypofibrinolysis as measured by ECLT in intensive care patients with and without sepsis." (PMID 15456513, 2004). "Moreover, no data is available in the NTDB about sepsis onset timing, time to antibiotic initiation, fluid resuscitation, adherence to sepsis protocols and key biomarkers (lactate, procalcitonin, CRP, caspase-1) which are essential for adequate sepsis management." (PMID 40901518, 2025). "Rather than relying on a single laboratory value, geriatric sepsis care may benefit from simple composite indicators; for instance, a combined magnesium-and-CRP threshold could be used to triage octogenarian patients at the highest risk of death or prolonged ICU needs." (PMID 41189164, 2025). "However, moCD38 showed AUC values of 0.82, 0.82, and 0.81 for distinguishing the Sepsis group, BS subgroup sepsis, and OS subgroup sepsis from the Mild group, respectively, with performance not surpassing clinical parameters such as CRP concentrations and PCT concentrations." (PMID 40145840, 2025). "The significant decline in GDF15 levels over the 10-day follow-up and its meaningful correlations with CRP and renal dysfunction indicators such as BUN, creatinine, and eGFR suggest that this biomarker may reflect not only the inflammatory response but also organ damage in sepsis." (PMID 40941711, 2025). "However, serum concentrations of this protein are not specific to gastrointestinal disease and, similar to CRP, may also be elevated in other systemic inflammatory conditions, including pancreatitis, sepsis, and hyperlipidemia." (PMID 40979161, 2025). "Notably, within the PPI network analysis, key proteins including ICAM1, Resistin, TIMP1, VWF, CRP, and HMGB1 were identified at the central nodes of the network module, revealing a significant difference (P < 0.05) between the normal group and the sepsis group." (PMID 38951753, 2024). "Numerous biomarkers, such as interleukin 6 (IL 6), interleukin 2 (IL 2), CRP, and PCT, have been extensively studied in an effort to distinguish infections from non-infectious causes of fever in sepsis patients, which could potentially aid in optimizing the use of antibiotics." (PMID 38681106, 2024). "This suggests that CRP may not be an ideal marker for acute changes in sepsis severity." (PMID 39507174, 2024). "A study involving 171 patients found that CRP levels measured a few days after admission, rather than initial concentrations, might be more useful in evaluating the treatment response and outcome of sepsis." (PMID 39459346, 2024).
Sepsis (continued). "Furthermore, the diagnostic performance of the MDW, CRP, and PCT as predictors of sepsis have been studied in association and individually, and the results have shown that the diagnostic ability of the MDW was not lower than those of the CRP and PCT in terms of the areas under the curve (AUCs)." (PMID 37629715, 2023). "Given the ongoing development of therapeutics that target trans-specific IL-6 signalling and therapeutics that target CRP itself, this may represent a future avenue in sepsis therapeutics; however, this does not alter the interpretation of the primary IL6R blockade-related finding here." (PMID 36716318, 2023). "Hence, as has been shown for CRP, higher plasma chemerin is not a specific sepsis marker." (PMID 37509420, 2023). "Given that the clinical symptoms or signs may not be evident even in sepsis, particularly old age or early visits, normal or low levels of initial CRP without simultaneous measurement of other biomarkers could allow late administration of antibiotics and lead to poor clinical outcomes." (PMID 36555941, 2022). "However, it had better accuracy than CRP and WBC count in identifying SBI in children, and it could perform better in identifying the most severe infections, such as bacterial meningitis and sepsis." (PMID 35626858, 2022). "Although a moderate or weak correlation was found between nCD64 index and SOFA, PCT, and CRP, which suggested that nCD64 index might be a useful marker for predicting disease severity in sepsis, it should be noted that nCD64 index is not a substitute for these commonly used indicators of infection." (PMID 35967346, 2022). "However, CRP may have a low specificity in diagnosing sepsis, because its serum concentration may increase in several non-septic inflammatory or non-inflammatory conditions." (PMID 34072427, 2021). "Thus, immune-related biomarkers, such as neutrophil-to-lymphocyte ratio (NLR), C-reactive protein (CRP), procalcitonin (PCT), sTREM-1, presepsin, cytokines, and various interleukins, are increasingly being evaluated for their abilities of early recognition and to predict prognosis of sepsis." (PMID 33796105, 2021). "However, negative imaging tests, nonresponse of fever, overall clinical condition, increasing C-reactive protein in spite of being on three different antibiotics, and development of the mucocutaneous features of Kawasaki disease confirms that this was not sepsis." (PMID 34158105, 2021). "Notably, plasma CRP levels were not correlated with CRP+ EVs in plasma from sepsis patients." (PMID 33772103, 2021). "The main limitation of their study is that they used clinical sepsis scores, haematological pictures, CRP, and ESR to confirm the diagnosis rather than microbiological cultures, which could explain the disparity between their results and the current study results." (PMID 34691286, 2021). "Our study results showed that CRP concentration in venous blood plasma did not significantly differ between two sepsis groups (EOS and LOS) and control group, indicating that this acute phase reactant protein may not be unreliable for early diagnosis of neonatal sepsis." (PMID 33521320, 2021). "Furthermore, a recent meta-analysis of data from 631 ICU patients, of whom 371 had infections or sepsis, confirmed that these conditions could be identified accurately based on PSP values [AUROCC = 0.81, slightly superior to those for PCT (0.78) and CRP (0.77)]." (PMID 33879189, 2021). "Moreover, the ROC curve illustrated that CRP (AUC [95%CI]: 0.755 [0.636–0.874]), TNF‐α (AUC [95% CI]: 0.660 [0.534–0.786]), IL‐1β (AUC [95% CI]: 0.665 [0.549–0.781]), and IL‐6 (AUC [95% CI]: 0.622 [0.507–0.737]) all had potential in discriminating sepsis deaths from sepsis survivors." (PMID 34761437, 2021). "Hence, moderate increases of CRP or moderate decreases of PON1 may not differentiate dogs with sepsis from dogs with non-septic conditions." (PMID 34072427, 2021).
Sepsis (continued). "In addition, the significant association between miR-103 and the clinical characteristics, including WBC, CRP, PCT, APACHE II score, and SOFA score, was found in sepsis patients, implying that miR-103 might be involved in the development and progression of sepsis." (PMID 32455124, 2020). "In this study, significantly elevated levelsof PCT, CRP and WBC were detected in septic patients, and their levels were found to be positivelycorrelated with serum expression of miR-451a, which suggested that miR-451a might be involved in thedevelopment of sepsis." (PMID 33211058, 2020). "Additionally, it has been shown that PCT rises faster than CRP; if the patient adequately responds to treatment, PCT can return to baseline levels faster than CRP, making it a preferred biomarker not only for diagnosis of sepsis but for trending appropriate care and patient improvement." (PMID 32467788, 2020). "Interestingly, not any combination of MRproADM with CRP, PCT, and/or IL6 could increase the diagnostic accuracy for sepsis (data not shown)." (PMID 32831638, 2020). "This may be related to the lack of specificity of CRP in both sepsis and nonsepsis patients." (PMID 33225902, 2020). "However, CRP can increase in both infectious and noninfectious diseases and, even though procalcitonin has a well-defined role as a sepsis biomarker, it has inconsistent and variable results for the diagnosis of infectious sepsis, not to mention it is expensive to assess." (PMID 31648506, 2019). "However, to distinguish between sepsis and non-infectious disease etiology, CRP lacks specificity, and elevated CRP serum levels are also common in patients with inflammatory (but not infectious) diseases states such as cancer, thromboembolic- or cardiovascular diseases, and burns." (PMID 31569348, 2019). "However, intrigued by the peculiar dynamics of the inflammatory markers during sepsis, especially the lack of IL-6 and CRP response along the high PCT elevation, we prompted investigation of the integrity of IL-6 signaling axis, which we tested in the following steps." (PMID 31781117, 2019). "Thus, our study was set out to investigate, in febrile children between 1 month to 5 years presented to ED, the diagnostic accuracy of used SIRS and sepsis markers, as WBC, neutrophils count, platelet count, CRP, NLR, PLR, MPV, as well as not so prevalent PLT/MPV." (PMID 30974881, 2019). "Also, criteria for culture negative sepsis varied, as the national survey did not include CRP values in the evaluation, and therefore may have overestimated the incidence of confirmed infections." (PMID 31709209, 2019). "Patients with negative outcome showed sustained CRP elevation, neutrophilia, lymphocytopenia, and low levels of mHLA-DR, supporting the theory of a dysregulated host response with persistent inflammation and immunosuppression in late stages of deleterious sepsis." (PMID 29466395, 2018). "Therefore, both PCT and CRP might be still not reliable enough as early indicators for sepsis used in the clinical context." (PMID 28875483, 2017). "However, whether PCT is still more useful than hs-CRP in diagnosing sepsis in oldest old patients has not been investigated." (PMID 28764651, 2017). "Also, another recent study comparing the prognostic accuracy of PCT, CRP, and WBC in 513 patients presenting to the ED with signs/symptoms of local infections or sepsis found PCT to be the most accurate biomarker for diagnosis of sepsis and for mortality prediction." (PMID 26656373, 2015). "However, as the value at 72 h was not significant, this demonstrated that the CRP/albumin ratio at 72 h may not be used as a tool to guide decisions on the treatment of patients with severe sepsis and septic shock." (PMID 26158725, 2015). "PCT could be used for diagnosing severe sepsis without shock with a larger AUC than CRP." (PMID 25960877, 2014).
Sepsis (continued). "The AUCs for IL-2, IL-6, IL-10 and CRP were 0.901 (95% CI, 0.866 to 0.930), 0.86 (95% CI, 0.821 to 0.894), 0.888 (95% CI, 0.851 to 0.918) and 0.848 (95% CI, 0.807 to 0.883) respectively, indicating that IL-2, IL-6 and IL-10 were effective biomarkers to rule out sepsis and intracranial infection." (PMID 24887408, 2014). "The gold standard to distinguish sepsis from non-infectious diseases is blood microbiological culture analysis, which is more time-consuming than other potential biomarkers for early detection of sepsis, including acute phase proteins such as C-reactive protein (CRP) and procalcitonin (PCT)." (PMID 23596477, 2013). "Four subgroup analyses are planned to analyze whether treatment effect is modified by age, vasopressor requirement (defined as any inotropic requirement except dopamine <6mcg/kg/minute); etiology of ALI (due to sepsis versus non-sepsis) and CRP level at baseline." (PMID 22985805, 2012). "Moreover, LBP and CRP may be clinically useful in critically ill neonates and children, where LBP has a high diagnostic accuracy to differentiate sepsis from non-infectious SIRS." (PMID 21901123, 2011). "Biomarkers such as C-reactive protein (CRP) and procalcitonin (PCT), which are the most widely used and studied, do not have the ability to predict mortality in sepsis patients." (PMID 40568710, 2025). "Concentrations of REG1A can reliably distinguish sepsis from non-septic SIRS, correlate well with disease severity, and can predict development of sepsis and non-survival, performing at least as well as CRP and PCT in several studies." (PMID 40392915, 2025). "Conventional inflammatory markers (hs-CRP, PCT, white blood cell count (WBC)) were significantly elevated in sepsis while platelets (PLT) showed a lower count compared with non-septic patients." (PMID 41462865, 2025). "In patients with leukopenia, the discrimination function of MDW to predict sepsis was not significantly different from that of PCT and CRP." (PMID 41303127, 2025). "The use of non-specific markers such as serum C-reactive protein (CRP) and procalcitonin (PCT), along with the clinical presentation, remains the most widely used method for sepsis diagnosis (Henriquez-Camacho and Losa, 2014)." (PMID 39857101, 2025). "For differentiating sepsis from non-sepsis in ICU patients, IL-8, ACSL4, GPX4, CRP, PCT, NEU%, IL-6, and PTGS2(p-value =0.007) exhibited significant diagnostic value (all p-value <0.00001)." (PMID 40264754, 2025). "First, the samples were processed in a consecutive way with the characteristics of inclusion: preterm babies without signs of sepsis but with a CBC and CRP test request due to clinical monitoring." (PMID 39978117, 2025). "Laboratory trends of PIICS criteria over time were compared between patients with and without sepsis regarding individually obtained results for ALC, albumin, and CRP." (PMID 40555121, 2025). "CRP is an acute responsive phase protein produced by the liver, while PCT is typically used to identify sepsis and non-sepsis." (PMID 40784366, 2025). "Logistic regression analysis identified C-reactive protein (CRP) and procalcitonin (PCT) as the most predictive biomarkers for distinguishing sepsis/septic shock from non-infectious SIRS patients, with score chi-square values of 15.97 and 13.68, respectively." (PMID 41153764, 2025). "For a 70-year-old sepsis patient with no background of CHF, the following factors were evaluated: INR, 0.83; fibrinogen, 4.87 g/L; CRP, 108 mg/L; SOFA score, 11, with no use of dopamine." (PMID 40621331, 2025). "Although Gal-9 was not superior to CRP in discriminating sepsis from NIOF, it performed better than CPR in discriminating septic shock from sepsis." (PMID 41225969, 2025). "Nonetheless, their study faced criticism due to the observed significant differences in presepsin, CRP, and WBC counts, but not in PCT levels, in the first 24 h of sepsis in contrast with previous days." (PMID 39982339, 2025).
Sepsis (continued). "Multiple studies have shown that CRP and PCT levels are not significantly correlated with 28-day mortality in patients with sepsis." (PMID 41169360, 2025). "While standard clinical parameters and inflammatory markers such as CRP, PCT, and IL-6 were elevated in both groups, they lacked the specificity to distinguish sepsis origin." (PMID 40510342, 2025). "In patients without malignancy, PCT achieved the highest AUC for sepsis discrimination (AUC of 0.909), followed by MDW (0.870) and CRP (0.794)." (PMID 41303127, 2025). "Patients with ICU-AW, as compared to those without weakness, were older, more likely to have sepsis or infection upon admission, more likely to have received steroids, presented higher SOFA PaO2/FiO2 and APACHE II score and higher CRP and creatinine levels." (PMID 41026286, 2025). "CVP, SOFA score, CRP, lactate, VIS, and RRI not reduction following 24h of ICU treatment can be utilized as predictive indicators for early detection of SA-AKI in sepsis patients." (PMID 39864312, 2025). "Our study confirms CRP, PCT, and sCD14-ST as the most reliable biomarkers for distinguishing sepsis from non-infectious SIRS, with sTREM-1 providing additional, though non-independent, diagnostic and monitoring value." (PMID 41153764, 2025). "A critical limitation of our study is the absence of contemporaneous measurement of established sepsis biomarkers (PCT, CRP, lactate) and clinical scoring systems (qSOFA, NEWS2, SOFA) within the same patient cohort." (PMID 41488103, 2025). "The multivariate logistic regression analysis showed that variables including CVP, SOFA score, CRP, lactate, VIS, and RRI not reduced following 24h of ICU treatment were predictive indicators for early detection of SA-AKI in sepsis patients." (PMID 39864312, 2025). "In the overall sepsis cohort, IPF correlated strongly with MPV, moderately with CRP, and inversely with platelet count, but not with PCT, ANC, plateletcrit, or MCV." (PMID 40723124, 2025). "In line, the prognostic value of CRP was studied in 313 patients admitted to the ICU, which was not restricted to patients with sepsis." (PMID 37204560, 2024). "All of them were significantly higher in patients with sepsis than in those without sepsis at several specific time points but only SAA, CRP, and PCT were found to be independently predictive of sepsis except IL-6 as shown in this study." (PMID 38182736, 2024). "The sepsis markers PCT and NLR also performed well with AUC of 0.743 and 0.717 respectively, while CRP had a non-significant AUC of only 0.543." (PMID 39108794, 2024). "BMP6 did not correlate with leukocyte numbers, procalcitonin, CRP, or IL-6 in the sepsis/septic shock group (p > 0.05 for all) or in the SIRS/sepsis/septic shock cohort when patients with liver cirrhosis were excluded." (PMID 39200147, 2024). "CRP and PCT were clinically reliable sepsis biomarkers in both culture-positive and culture-negative patients." (PMID 38774176, 2024). "Biological indicators of inflammation, including CRP, PCT, and interleukins, offer some indication of disease in patients, but are not specific enough to determine infection and sepsis in infant cohorts." (PMID 39335050, 2024). "Patients with sepsis had significantly higher mean values for leukocyte count, NLR, MDW, CRP, and PCT levels than those without sepsis (p < 0.05)." (PMID 39336599, 2024). "Patients with sepsis displayed higher levels of PCT and PSP than patients without sepsis at each timepoint; differently, CRP displayed statistically significant differences only at T0, while MDW only at T0 and T24." (PMID 38831992, 2024). "CRP, WBC, and lactate blood tests add minimal predictive value in distinguishing sepsis or determining non-conveyance eligibility." (PMID 39379809, 2024). "The present study confirms no prognostic impact of CRP and PCT levels in patients with sepsis and septic shock - which is line with reports from our study group from the year 2004." (PMID 37204560, 2024).